TNF (tumor necrosis factor)
Diseases named in the same sentence as TNF in open-access papers (continued):
Sharing a sentence is not in itself a finding about the gene and the disease.
rheumatoid arthritis (continued). "Moreover, it has been described that in patients with rheumatoid arthritis Tph lymphocytes are able to release, in addition to IL-21, Th1-type pro-inflammatory cytokines (such as interferon-γ, tumor necrosis factor-α and granulocyte/monocyte colony stimulating factor)." (PMID 38878190, 2024). "TNF-alpha plays a major role in homeostasis and the maintenance of the immune system, but during the middle and old age stages of life, it can contribute to chronic inflammation, being abundantly expressed in conditions such as rheumatoid arthritis and bipolar disorder." (PMID 38760355, 2024). "TNF-α inhibitors like infliximab and etanercept are effective in treating Crohn’s disease and rheumatoid arthritis (RA)." (PMID 37196131, 2024). "The gene encoding pro-inflammatory cytokines such as IL-1, IL-2, IL-6, Tumor necrosis factor (TNF)-α, and Monocyte chemoattractant protein (MCP)-1 play significant roles in increasing the risk of chronic diseases such as asthma, atherosclerosis, and rheumatoid arthritis." (PMID 38164478, 2024). "We report a case of a 67-year-old man with PG and severe ankle ankylosis complicated by rheumatoid arthritis (RA) treated with anti-tumor necrosis factor, adalimumab (ADA)." (PMID 39803031, 2024). "In addition, ORA for KEGG pathways revealed a statistically significant overrepresentation of these genes belonging to four pathways: TNF signaling pathway (Padj = .003), IL-17 signaling pathway (Padj = .011), rheumatoid arthritis (Padj = .039), and PPAR signaling pathway (Padj = .041)." (PMID 39850030, 2024). "The objective of the study was to determine the optimal threshold of the proportion of days covered (PDC) for tumor necrosis factor (TNF) inhibitors in patients with rheumatoid arthritis (RA)." (PMID 38853227, 2024). "In addition, it is important to highlight the fact that the levels of circulating TNF, which is involved in the pathogenesis of various systemic diseases, can link periodontitis to conditions such as diabetes and rheumatoid arthritis, thus exacerbating systemic inflammatory processes." (PMID 38920850, 2024). "As an example, YKL-40 can be upregulated by proinflammatory cytokines, including tumor necrosis factor-α, which is a potential therapeutic target for patients affected by rheumatoid arthritis (RA)." (PMID 39045410, 2024). "Notably, following the systemic administration of GRP78 or its analog IRL201805 in an animal model of rheumatoid arthritis, these proteins are rapidly internalized by monocytes, which eventually leads to an increased secretion of IL-10 and the suppression of TNF-α and IL-1β release." (PMID 38612761, 2024). "In our present study, we aimed to assess the effects of anti-TNF therapy on periodontal condition in a mixed cohort of patients with rheumatoid arthritis (RA) and ankylosing spondylitis (AS)." (PMID 38256582, 2024). "Therefore, we believe that prospective studies with larger sample sizes, that analyze the role of anti-TNF inhibitors, homocysteine and 25-OH-vitamin D levels in the trabecular bone score, are necessary for better management of rheumatoid arthritis patients and the complications of this disease." (PMID 38672734, 2024). "EA alleviates the inflammatory reaction by reducing the levels of serum pro-inflammatory cytokines such as IL-1, IL-1β, IL-6, IL-17, IL-23, and TNF-α in rheumatoid arthritis (RA) animal models and IL-17 in the peripheral blood of RA patients." (PMID 39335365, 2024). "Adalimumab, a tumor necrosis factor inhibitor (TNFi), received approval from the U.S. Food and Drug Administration for use in rheumatoid arthritis (RA) in 2002, ankylosing spondylitis in 2006, and juvenile idiopathic arthritis (JIA) in 2008." (PMID 39734203, 2024).
rheumatoid arthritis (continued). "IFN-γ, identified in rheumatoid arthritis, inhibits osteoclast formation and maturation, influencing osteoblasts and mesenchymal stem cells in a complex manner, promoting osteogenic differentiation but, in synergy with TNFα, inhibiting both osteogenic and adipogenic differentiation." (PMID 38474093, 2024). "However, prior pre-clinical studies of pathogenic cytokines (e.g., TNF) in inflammatory diseases have led to the Nobel Prize -Winning anti-TNF therapies for patients with rheumatoid arthritis, inspiring an improved understanding of the complex pathogenic mechanism of sepsis." (PMID 39763679, 2024). "TNFα inhibitor (TNFi) immunogenicity in rheumatoid arthritis (RA) is a major obstacle to its therapeutic effectiveness." (PMID 39850568, 2024). "Etanercept received approval from the US Food and Drug Administration (FDA) in November 1998 as the first anti-tumor necrosis factor agent for the treatment of moderate to severe rheumatoid arthritis (RA)." (PMID 39311381, 2024). "Compared to other cytokines such as interleukin-1 (IL-1) and tumor necrosis factor (TNF), anti-IL-6 therapy is more effective in improving serum lipoprotein levels in patients with rheumatoid arthritis (RA)." (PMID 39749325, 2024). "Furthermore, KEGG pathway analysis demonstrated that up-regulated co-DEGs participated in chemokine signaling pathway, cytokine-cytokine receptor interaction, IL-17 signaling pathway, rheumatoid arthritis, NF-κB signaling pathway, TNF signaling pathway, and Toll-like receptor signaling pathway." (PMID 38321132, 2024). "We retrospectively review a case of a patient with rheumatoid arthritis with a newly diagnosed GPA with RA on anti-TNF therapy." (PMID 39583403, 2024). "Furthermore, BBR was shown to regulate the proliferation and adhesion of RA-FLS cells through the RAS/MAPK/FOXO/HIF-1 signaling pathway, as well as reduce the expression of matrix metalloproteinase (MMP)-1, MMP-3, RANKL, and TNF-α, thereby combating rheumatoid arthriti." (PMID 38957396, 2024). "Adalimumab (ADM), a fully human monoclonal antibody that neutralizes tumor necrosis factor-α (TNF-α), was initially approved for the treatment of moderate to severe rheumatoid arthritis (RA) in 2002." (PMID 39040471, 2024). "For example, synovial fibroblasts from patients with rheumatoid arthritis (RA) produce EVs containing the inflammatory protein TNF-α and stimulate NFkB production." (PMID 38203656, 2023). "Justifications or motivations for conducting a drug discontinuation trial from the investigators point of view could be grouped in seven categories: the most frequently given reason for conducting a DDT were concerns for drug toxicity [e.g., rheumatoid arthritis treatment with TNF inhibitors (49%)." (PMID 36703178, 2023). "The recent Oral Rheumatoid Arthritis Trial (ORAL) Surveillance study of RA patients showed that tofacitinib (a JAKi) was associated with a greater risk of cancers and major adverse cardiovascular events (MACE) than tumor necrosis factor inhibitors (TNFis)." (PMID 37080728, 2023). "LINC-PINT is downregulated in rheumatoid arthritis (RA) tissues and TNF-α stimulated RA cells, increasing SOCS1 expression by inhibiting the activation of the ERK signaling pathway in RA synovial fibroblasts induced by TNF-α by sponging miR-155-5p." (PMID 37553573, 2023). "Rheumatoid arthritis (RA) patients are another example of treatment-related immunosuppression, as they are frequently treated with either cyclosporin or tumor necrosis factor (TNF) antagonists." (PMID 36980651, 2023). "Peripheral whole blood from both healthy donor and rheumatoid arthritis (RA) patients were stimulated with tumor necrosis factor-α (TNF-α), and cells analyzed by mass cytometry." (PMID 35997780, 2023).
rheumatoid arthritis (continued). "On closer inspection, inflammatory biomarkers such as TNF‐a and IL‐1 have several common pro‐inflammatory properties, such as prostaglandin E2 (PGE2) production as well as the activation of collagenase, which in cases such as rheumatoid arthritis can cause joint damage." (PMID 37324871, 2023). "The results were consistent with a study in patients with rheumatoid arthritis, showing that tocilizumab treatment normalized the molecular signature at whole blood transcriptome levels to a greater extent than treatment with methotrexate or a tumor necrosis factor inhibitor." (PMID 36597161, 2023). "This is because a number of anti-TNF agents, including infliximab, etanercept, adalimumab, certolizumab pegol, and golimumab, are widely used to treat inflammatory diseases such as inflammatory bowel disease, rheumatoid arthritis, ankylosing spondylitis, psoriatic arthritis, and psoriasis." (PMID 37290815, 2023). "Excessive JAK/STAT stimulation by cytokines such as IL-1, IL-6, IL-15, TNF-α, and IFN has been associated with rheumatoid arthritis (RA), multiple sclerosis, inflammatory bowel disease, and periodontal disease, to name a few." (PMID 37373437, 2023). "Rheumatoid arthritis (RA) patients are currently treated with biological agents mostly aimed at cytokine blockade, such as tumor necrosis factor-alpha (TNFα)." (PMID 38187379, 2023). "In previous work, it has been shown that UDP-G promotes CTX of normal human neutrophil PMNs, and such activation was most pronounced in PMNs preincubated with serum from patients with rheumatoid arthritis (RA) and high levels of TNF-α." (PMID 37895972, 2023). "It is also used to treat rheumatoid arthritis (RA) and this was attributed to its anti-inflammatory property in reducing key proinflammatory cytokines of RA – interleukin-6 (IL-6) and TNF-α, matrix metalloproteinases (MMPs) and prostaglandin E2." (PMID 36911685, 2023). "The GSEA analysis revealed that DEGs were inversely associated with the HIF-1 signaling pathway, the TNF signaling pathway, the AGE-RAGE signaling pathway, the NF-kappa B signaling pathway, ferroptosis, the IL-17 signaling pathway, ovarian steroidogenesis, and rheumatoid arthritis." (PMID 37350944, 2023). "Several retrospective studies and meta-analyses of patients with rheumatoid arthritis treated with TNF inhibitors have shown that TNF inhibitors are not directly associated with the development of solid tumors, but the risk of developing non-melanoma skin cancer can be increased to 1.4- to 2- fold." (PMID 37485474, 2023). "TNFα is one of the proinflammatory cytokines that has a complex role in the pathogenesis of rheumatoid arthritis (RA)." (PMID 37046333, 2023). "Results of our experiments show that Jinwujiangu prescription's effect on RA was related to TNF signaling pathway, rheumatoid arthritis, IL-17 signaling pathway, NF-κB signaling pathway, and Toll-like receptor signaling pathway." (PMID 36816744, 2023). "Rheumatoid arthritis (RA) is a complex autoimmune disease that is also driven by innate immune pathology (e.g., overproduction of tumor necrosis factor; TNF), which together contribute to joint inflammation, pain, and connective tissue destruction." (PMID 37691918, 2023). "TNFα has been shown to play an essential role in the pathogenesis of autoimmune diseases such as rheumatoid arthritis (RA), psoriatic arthritis (PSA), and ankylosing spondylitis (AS)." (PMID 37554981, 2023). "Our study will probe into the function of PNX-20 on tumor necrosis factor α (TNF-α)- induced rheumatoid arthritis (RA) FLS cell senescence to provide a theoretical basis for treating RA with PNX-20." (PMID 38112587, 2023). "A relapse after an initial response to TNF-a antagonist therapy may indicate either drug-induced granulomatous disease or the development of antidrug antibodies, as reported with infliximab or adalimumab in patients with rheumatoid arthritis." (PMID 37250639, 2023).
rheumatoid arthritis (continued). "Thus, anti-TNF-α monoclonal antibodies are broadly used and are efficient in particular for the treatment of rheumatoid arthritis (RA), inflammatory bowel disease (IBD), psoriasis, psoriatic arthritis, ankylosing spondylitis (AS), and juvenile idiopathic arthritis (JIA)." (PMID 37373525, 2023). "Tumor necrosis factor (TNF) inhibitors are a class of anti-inflammatory drugs that have been used in immunologically driven musculoskeletal conditions characterized by inflammation, including rheumatoid arthritis (RA), psoriatic arthritis and juvenile idiopathic arthritis." (PMID 37649531, 2023). "Anti-tumor necrosis factor (TNF) treatment has improved the quality of life of people with inflammatory diseases such as Rheumatoid arthritis (RA), Crohn’s disease, and ulcerative colitis." (PMID 38268817, 2023). "Anti-TNF therapeutics have been used as a first-line biological treatment of a variety of inflammatory diseases, including rheumatoid arthritis (RA), psoriasis, and inflammatory bowel disease (IBD)." (PMID 37662935, 2023). "In 2022, the Oral Rheumatoid Arthritis Trial (ORAL surveillance study) found a higher risk of major adverse cardiovascular (CV) events and venous thromboembolic events (TVE) in patients with RA and CV risk factors treated with Xeljanz (tofacitinib) than with Tumor Necrosis Factor inhibitors (TNFi)." (PMID 37448804, 2023). "Thus, targeting IL-6 and/or TNFα offers approaches to the diagnosis and treatment of different primary diseases (e.g., rheumatoid arthritis and sarcopenia) and health-compromising secondary conditions (e.g., cancer cachexia and post-infectious acute respiratory distress syndrome, ARDS)." (PMID 36830664, 2023). "In rheumatoid arthritis (RA), IL-17-producing Th17 cells reportedly induce local inflammation by stimulating production of IL-6, IL-1, TNFα and chemokines, and IL-17 may directly stimulate synovial fibroblasts to induce RANKL expression, which in turn, results in bone destruction." (PMID 38062130, 2023). "Our results agree with other PRGF applications that inhibit the TNFα and IL-1β production by using in vitro rheumatoid arthritis (RA) model." (PMID 36009539, 2022). "Rheumatoid arthritis (RA) is an autoimmune disease characterized by inflammatory bone destruction in which tumor necrosis factor alpha (TNF-α) plays a key role." (PMID 35148358, 2022). "Non-response to anti-TNF therapy usually represents loss of disease control in patients with severe rheumatoid arthritis, as well as unnecessary exposure to potentially severe adverse effects of anti-TNF drugs and inefficient use of expansive biological therapeutics." (PMID 36009355, 2022). "Circulating levels of chondroitin/dermatan sulfate (CS/DS) and heparan sulfate/heparin (HS/H) in healthy subjects and patients with rheumatoid arthritis (RA) before and after 15-month anti-TNF-α therapy." (PMID 35887981, 2022). "Oral administration of liposomal bovine lactoferrin (LbLf) effectively prevents the progression of rheumatoid arthritis (RA) in mice by inhibiting tumor necrosis factor (TNF-α) production in the pancreas." (PMID 36712548, 2022). "TNF inhibitors (TNFi) are used clinically to counterbalance the high TNF levels in several autoimmune rheumatic diseases such as rheumatoid arthritis (RA)." (PMID 35647193, 2022). "Chronic treatment with infliximab, an anti-TNF-α antibody, prevented endothelial dysfunction of the brachial artery in patients with rheumatoid arthritis (RA), systemic vasculitis and Crohn’s disease." (PMID 35206342, 2022). "Anti‐TNF medications are used to treat a number of other immune‐mediated inflammatory diseases, which together affect about 5%–7% of Western populations including rheumatoid arthritis, ankylosing spondylitis, psoriatic arthritis, psoriasis, hidradenitis suppurativa and uveitis." (PMID 35768996, 2022).
rheumatoid arthritis (continued). "However, we will not be surprised to see the future applicability in other autoimmune diseases like rheumatoid arthritis because predictors may well indicate the TNFα’s origin and release dynamics." (PMID 35517818, 2022). "Similarly, protein subsets also revealed several enriched GO terms that were not previously directly associated with anti-TNF therapy response in rheumatoid arthritis." (PMID 36009355, 2022). "In view of the crucial role of tumor necrosis factor (TNF) in joint destruction, TNF inhibitors, including neutralizing anti-TNF antibodies and soluble TNF receptor constructs, are commonly used therapeutics for the treatment of arthropathies like rheumatoid arthritis (RA)." (PMID 36389831, 2022). "A cross-sectional design of rheumatoid arthritis (RA) patients found that serum levels of NPY are significantly related to TNF-α levels and disease activity in RA independently of IL-6, TNF-α, or leptin levels." (PMID 35273572, 2022). "In rheumatoid arthritis (RA) models, TQ reduced the expression of IL-1, TNF-α, bone turnover markers, alkaline phosphatase, and tartrate-resistant acid phosphatase, which indicates the proper balance in the bone sorption and resorption activities." (PMID 36354542, 2022). "TNF inhibitors (TNFi), including neutralizing monoclonal anti-TNF antibodies and soluble TNF receptor constructs, have revolutionized the treatment of rheumatoid arthritis (RA) and spondyloarthritis (SpA) in the clinical setting." (PMID 36389831, 2022). "TNF is a key mediator in autoimmune diseases and during the last couple of decades several biologic drugs have delivered new therapeutic options for patients suffering from chronic autoimmune diseases such as rheumatoid arthritis and chronic inflammatory bowel disease." (PMID 36467083, 2022). "Monocytes/macrophages are key players in the pathogenesis of rheumatoid arthritis (RA) by secreting tumor necrosis factor α (TNF-α) among other inflammatory cytokines." (PMID 35281074, 2022). "HDAC 1 levels are elevated in synovial fluid of rheumatoid arthritis (RA) patients, and HDAC 1 levels correlate with the expression of TNF-α in RA synovial tissues." (PMID 35997393, 2022). "Infliximab and golimumab are intravenously (IV) administered tumor necrosis factor inhibitors approved to treat moderate-to-severe rheumatoid arthritis (RA) with concomitant methotrexate." (PMID 35312895, 2022). "Thus, in addition to the inhibitor of Wnt/β-catenin signals, sclerostin may have a role in the suppression of TNF-induced inflammation in rheumatoid arthritis." (PMID 35563281, 2022). "The rationale for using anti-TNF drugs in rheumatoid arthritis (RA), inflammatory bowel disease (IBD) and psoriasis centered on clinical and experimental data linking pro-inflammatory activities of TNF to non-resolving inflammation." (PMID 35027468, 2022). "The treatment of rheumatoid arthritis (RA) has advanced from the use of steroids to disease-modifying anti-rheumatic drugs (DMARDs) and biologics such as tumor necrosis factor (TNF) and interleukin-6 (IL-6) inhibitors." (PMID 36168347, 2022). "Fibroblast-like synoviocytes (FLS) derived from patients with rheumatoid arthritis (RA) displayed enhanced production of certain cytokines and chemokines when preexposed to TNFα and subsequent interferon (IFN) stimulation." (PMID 35941890, 2022). "Golimumab, a novel human anti-TNFα IgG1κ mAb, is safe for the treatment of psoriatic arthritis (PsA), rheumatoid arthritis (RA), and ankylosing spondylitis (AS)." (PMID 35449588, 2022). "This provides a target for therapeutic intervention by blocking the action of TNFα; for example, with antibodies against TNFα such as infliximab, which is already being used in clinical practice to reduce peripheral inflammation in diseases such as rheumatoid arthritis or Crohn’s disease." (PMID 35911759, 2022).